CAV1 (caveolin 1)
Diseases named in the same sentence as CAV1 in open-access papers (continued):
Sharing a sentence is not in itself a finding about the gene and the disease.
tumor (continued). "Expression of CAV1 in TSCC had a higher score in TME than in the tumor cells and a negative impact on recurrence (p = 0.01) and survival (p = 0.003)." (PMID 25633184, 2015). "Of these, CAV1, SFRP2, TMEFF2, SST and SLIT2 have been identified as tumor-suppressor genes." (PMID 25997610, 2015). "Independent of the Gleason score Cav1 was highly expressed in tumor ECs in all tissue specimen investigated." (PMID 25985209, 2015). "For tumor cells metastatic programs, the expression of FOXM1 may regulate a series of interrelated events including the expession of caveolin-1, VEGF, MPP-2 and MPP-9, which are important to epithelial–mesenchymal transition (EMT), angiogenesis and metastasts." (PMID 25935853, 2015). "“R1” tumours specimen which express weak or no Cav1 exert α5 integrin subunit staining confirming in vitro data." (PMID 26474461, 2015). "A majority of “non-R1” specimens showed > 75% of Cav1-positive cells, whereas no “R1” tumours belonged to that later category." (PMID 26474461, 2015). "A negative correlation was found between circulating tumor cells and stromal Cav-1 expression (P<0.05)." (PMID 24949874, 2014). "Hence, activity of stromal factors acting on proteasome pathways in tumor cells can occur in ARMS patients and be responsible of CAV1 downregulation." (PMID 25313138, 2014). "In this respect, our results implicate CAV1 expression in tumour cells at the initial site as a negative prognostic marker for surgery outcome because of the enhanced metastatic potential of these cells." (PMID 24500501, 2014). "The relationships of age, sex, histological grade, and tumor size with stromal Cav-1 expression were not significant (P>0.05)." (PMID 24949874, 2014). "Because proliferating myoblasts express CAV1, we postulated that very low or no expression on proliferating tumor cells suggest that CAV1 would have suppressive activities on ARMS." (PMID 25313138, 2014). "The distribution of the signal of Cav-1 in fibroblasts is random and has no relation with the Cav-1 status in tumor cells." (PMID 23527097, 2013). "Whereas, Cav-1 level in tumor cells failed to predict death, with area under the curve of 0.551 (95% CI: 0.438–0.664; P = 0.393)." (PMID 23527097, 2013). "Low expression of Cav-1 in CAFs but not in tumor cells independently prognosticated early recurrence and poor survival of GC patients." (PMID 23527097, 2013). "Ectopic expression of PTRF in endogenously Cav-1-expressing PC3 restores caveola formation, alters the cell proteome and secretome, significantly reduces cell migration and protease production and reduces in vivo tumor growth and metastasis." (PMID 24123650, 2013). "Low expression of Cav-1 in CAFs but not in tumor cells was an independent predictor of poor prognosis in GC patients (P = 0.034 and 0.005 respectively in disease free survival and overall survival)." (PMID 23527097, 2013). "Cav-1 expression gradually decreases with the progression of GC and the expression level in CAFs rather than in tumor cells to a certain extent predicts recurrence and survival in GC patients." (PMID 23527097, 2013). "Kaplan-Meier survival analysis revealed patients with Cav-1 positive tumours had a mean DFS of 4.72 yrs versus 6.35 yrs (P = 0.013) for patients with Cav-1 negative tumours." (PMID 24119769, 2013). "Kaplan-Meier analysis and the log-rank test showed that low expression of Cav-1 in CAFs rather than in tumor cells predicted poor survival." (PMID 23527097, 2013). "On the contrary, tumor cells Cav-1 level failed to prognosticate GC patient’s recurrence and survival in the simultaneous model." (PMID 23527097, 2013). "Coherently,—as Cav1 does not directly play as oncogene or full tumour suppressor molecule—they do not show signs of hyperproliferation." (PMID 23521716, 2013).
tumor (continued). "We found that the differences in Cav-1 expression were a result of tumor cell Cav-1 rather than stromal Cav-1." (PMID 22356861, 2012). "To date, limited clinical evidence is available to support a potential negative role for tumor EC-expressed Cav-1 in tumor-induced angiogenesis in humans." (PMID 26605130, 2012). "Caveolin 1 (CAV1) and FOS-like antigen 2 (FOSL2) expressions have been shown to be elevated in many human cancer cell lines and numerous human tumor specimens, thereby indicating that CAV1 and FOSL2 play important roles in the promotion of mammary tumorigenesis." (PMID 23023193, 2012). "Three (caveolin-1, cyclin B1 and Src-pY527) of four marker signature that differentiates NSCLC from normal lung in Nanjundan's study were also significantly different between normal and tumor tissues of the current studies." (PMID 22348039, 2012). "Although we have not extensively characterized the lung metastases these lesions do appear to have an epithelial morphology and thus if the tumor cells in the metastases are primarily epithelial we would not expect them to express high levels of Cav-1." (PMID 22356861, 2012). "Thus, our data suggest that overexpression of cav-1 in IBC cells contributes to proteolytic events involving CTSB that lead to ECM degradation, tumor invasion and metastasis." (PMID 21199580, 2011). "Our current findings show that cathepsin B and caveolin-1 were co-expressed in tumor cells of IBC patient samples and not in those of non-IBC patients." (PMID 22093547, 2011). "A major difference between prostate and kidney tissue is that CAV1 is present at high levels in normal kidney tissue independent of CAV1 levels in tumor tissue but not in normal prostate tissue." (PMID 22152020, 2011). "Although ST7 and CAV1 have been reported to be candidate tumor suppressor in several types of cancer, no direct evidences support their relationship with gastric carcinogenesis." (PMID 20626849, 2010). "Notably, expression of caveolin 1 (Cav1) and AXL receptor tyrosine kinase (Axl) is of therapeutic importance as is Cav1, known as tumour suppressor where it functions as a negative regulator of the Ras-p42/44 MAP kinase cascade." (PMID 21152443, 2010). "Besides contribution of Cav-1 in HCC cell motility and invasiveness, there was a strong correlation between differentiation status and Cav-1 expression in both HCC cell lines and tumor samples used in this study." (PMID 19239691, 2009). "Moreover, we observed a statistically significant positive correlation between venous invasion and Cav-1 expression in HCC tumor samples and showed that motility status of HCC cell lines are positively correlated with Cav-1 expressions in these cell lines." (PMID 19239691, 2009). "Examination of human HNSCC tumour tissues revealed significantly lower levels of Cav-1 in LNM than in the primary tumours with and without LNM." (PMID 19002186, 2008). "With endothelial cells as a positive control, Cav-1 staining was detected in all tumour cells of the CavS tumour tissues but was negative in all tumour cells of the EV tumour tissues." (PMID 19002186, 2008). "A possible explanation for these discrepancies is that caveolin-1 functions as a tumour suppressor in systems where negative signalling events downstream of caveolin-1 prevail." (PMID 18400052, 2008). "We did not observe any significant correlation of Cav-1 expression with tumour stage and survival rate, as we were unable to stratify the patients due to treatment and limited sample size." (PMID 19002186, 2008). "In our study, neither oestrogen receptor status, nor tumour stage, nor other clinical or pathological parameters, besides multifocality (p = 0.008), correlated with Caveolin-1 expression." (PMID 17915016, 2007). "In tumour prone mice lacking caveolin-1, the frequency and size of the lesions were greatly increased, while this was not true for mice heterozygous for caveolin-1." (PMID 18949068, 2007).
tumor (continued). "The molecular mechanism(s) of how cav-1 regulates tumor cell migration and metastasis has not been thoroughly explored." (PMID 15969750, 2005). "To determine whether cav-1 expression plays a central role in cell migration and invasion we chose the BxPC-3 and HPAF-II cell lines to represent tumor cells derived from primary tumors and metastases, respectively." (PMID 15969750, 2005). "Immunohistochemistry for caveolin-1 was performed on sections of peripheral tumour from 114 consecutative nonmetastatic RCCs." (PMID 14612902, 2003). "The relationship between positive caveolin-1 expression within this particular patient cohort and other excepted clinicopathological prognostic variables currently used in RCC is similar to other pathological findings conducted on other tumour types." (PMID 14612902, 2003). "We conclude that cytoplasmic overexpression of caveolin-1 predicts a poor prognosis in RCC; that this is likely to be a useful prognostic marker and that it may have importance in tumour progression." (PMID 14612902, 2003). "In summary, we have shown that elevated immunoexpression of caveolin-1 is a predictor of poor disease-free survival in RCC, suggesting that cell signalling pathways involving caveolin-1 may have importance in tumour progression." (PMID 14612902, 2003). "Collectively, these findings uncover a non-metabolic role of GLS1 in promoting tumor angiogenesis through exosome-mediated CAV1-TNC signaling, suggesting that targeting GLS1 may simultaneously inhibit tumor metabolism and angiogenesis in HNSCC." (PMID 42070227, 2026). "HPK may have utility for distinguishing distinctly different transport mechanisms in endothelia versus tumour cells entailing non-degradative CAV1-dependent transendothelial transport followed by tumour entry through an endosomolytic pathway." (PMID 39984637, 2025). "In summary, the ketogenic diet led to a significant decrease in both the expression of CAV1 and SLC7A11 at the single-cell level and their overall positive rate in tumor tissues, which also significantly reduced the tumor burden through inducing ferroptosis in tumor-bearing mice." (PMID 40180904, 2025). "Thus, there is an evident gradient of increasing CAV1 expression from the bulk of the non-budding cases, to the bulk of the budding cases, and finally to the tumor buds themselves." (PMID 40082664, 2025). "Notably, BPH tissue showed abundant stromal cav-1 immunostaining, whereas CaP showed an absence of stromal cav-1 directly correlating with CaP progression, as tumor metastases have been shown as negative for stromal cav-1 immunostaining." (PMID 39857963, 2025). "HerOND but not NIR-OND overlapped considerably with HER3 and CAV1 in tumour regions." (PMID 39984637, 2025). "In summary, the role of Cav1 in cancer, in particular the comprehension of the canonical (Cav1 located in the plasma membrane) and non-canonical pathways (Cav1 situated in organelles and exosomes), is connected to the protein’s double function as tumor suppressor and facilitator of metastasis." (PMID 38397421, 2024). "Three tumor markers for SCLC were measured in drug-sensitive H69 and drug-resistant VPA cells treated with EB and compared with untreated cells: neuron-specific enolase (NSE), caveolin-1 (CAV), and avian myelocytomatosis viral oncogene lung carcinoma-derived homolog (MYCL1)." (PMID 39594767, 2024). "In line with this, some authors suggested that high CAV1 expression in tumor cells and a lack of this expression in stromal cells could help identify a particular subgroup of BC patients with potentially poor survival." (PMID 39596307, 2024).
tumor (continued). "As a master regulator of signal transduction, CAV1 plays an essential role in tumor-stroma interactions, hypoxia response, cellular metabolism, inflammation, and epithelial-mesenchymal transition (EMT), which are critical drivers of tumor progression and metastasis." (PMID 38959243, 2024). "Taking the controversial role of CAV1 function in cancer development, as tumor suppressor or oncogene, in the present study, we focused on elucidating its impact in TNBC prognosis according to the intratumoral compartment where it is expressing: in cytoplasm of tumor cells or in tumor stroma." (PMID 39596307, 2024). "In line with this study, we observed that HNSCC tumor cells expressing caveolin-1 could use EREG silencing, but not AREG silencing, to overcome oncogenic dependence on EGFR and develop resistance to CTX/irradiation combination therapy." (PMID 36899869, 2023). "In a study conducted on different cancer cell lines, it has been established that caveolin-1-dependent tumor suppression, especially in the absence of E-cadherin, is linked to reduced HIF1α transcriptional activity via diminished NOS-mediated HIF1α S-nitrosylation." (PMID 38067108, 2023). "Thus, the significant decrease in CAV1 expression level in BM-MSCs after co-cultivation with SH-SY5Y cells demonstrated a decrease in the differentiation capacity of BM-MSCs, as evidenced by the recruitment of BM-MSCs to tumor cells." (PMID 36354566, 2022). "Tumor cells detached from the ECM, upon invasion through the basement membrane, and entering into the circulatory system, encounter blood flow‐induced low shear stress (LSS; 2 dyn/cm2), which induces expression of Caveolin‐1 (Cav‐1), a 22‐kDa integral membrane protein." (PMID 35992829, 2022). "Furthermore, as tumor-derived EVs also carry pro-EMT factors, including TGFβ, caveolin-1, HIF1α and β-catenin, our reported findings of reduced EV release in MDA-MB-231 miR-21 KO cells may play some roles in EMT." (PMID 33557112, 2021). "Cav-1 and other markers of the RWE represent promising targets for new combinations of therapies that work by ’uncoupling’ tumor cells from CAFs by preventing stromal Cav-1 degradation which may also have the ability to attenuate immunosuppression for immune therapies." (PMID 34813586, 2021). "The interaction of DLC1 with Caveolin-1 was found to be essential for DLC1 to inhibit migration and anchorage-independent growth but not to affect the DLC1 RhoGAP activity, representing another example of a RhoGAP-independent mechanism of DLC1 tumor suppressor activities." (PMID 34727930, 2021). "We hypothesized that the ratio of the isoforms of Cav-1 to each other differs between normal fibroblasts and CAFs in patients with OSCC and that this shift in the expression of the isoforms in the tumor microenvironment may contribute to tumor development and progression." (PMID 33774714, 2021). "There are no studies showing the expression of isoforms of Cav-1 in relation to tumor stages." (PMID 33774714, 2021). "Interestingly, recent studies have shown that Cav-1 may play a dual role in PDAC biology depending on the site of expression of the protein, tumor type, and stage of the disease." (PMID 34590611, 2021). "For example, tissue from both the primary tumor and metastatic site was not available in any patient, so we could not compare Cav-1 expression between primary tumor and metastases in the same patient." (PMID 34590611, 2021). "However, CAV1 suppresses tumor growth even in the absence of E-cadherin expression, albeit less efficiently." (PMID 32825247, 2020). "In addition, Macrocybin treatment resulted in the upregulation of Caveolin-1 expression and the disassembly of the actin cytoskeleton in tumor cells (but not in normal cells)." (PMID 33353176, 2020). "Thus, we evaluated how CAV1 expression in tumor cells lacking E-cadherin modulates responses in a hypoxic microenvironment where HIF is induced." (PMID 32825247, 2020).
tumor (continued). "In a preliminary bilateral tumor model, animals sequentially injected with biomarker-specific nanoprobes demonstrated preferential accumulation of target specific probes to their respective tumors: CXCR4 targeted probes to MCF7 cells and CAV1 targeted probes to 4175TR cells." (PMID 33172421, 2020). "This panel included the vascular marker CD31, CAF markers (CD34, caveolin-1 (CAV-1) and alpha smooth muscle actin (αSMA)) and steroid hormone receptors (SHR: androgen receptor (AR), progesterone receptor (PR) and estrogen receptor alpha (ERα)) in paired prostate non-tumour (PNT) and PCa tissue." (PMID 33370412, 2020). "CAV1 showed a corresponding enrichment in hypoxic compared with normoxic exosomes in vitro and in GBM patients compared with control exosomes; IL8 was found in quantity 3.4-fold higher in GBM tumor-bearing mice compared with control mice and accumulated in the hypoxic regions of GBM xenografts." (PMID 33086616, 2020). "Specifically, Chao and colleagues observed high levels of CAV1 in this type of cancer and noted that sensitivity to treatment with an antibody–drug conjugate, known as trastuzumab emtansine or T-DM1, mainly depended on the vesicle-trafficking properties of the tumor cells." (PMID 32458269, 2020). "Meanwhile, CAV1 could block the EGF-induced β-catenin-mediated transactivation and repress the transcription of cyclinD1, thus suppressing the cell cycle progression and tumor proliferation." (PMID 32386516, 2020). "Furthermore, oxidative stress in tumor cells induces the activation of pro-autophagy factors, such as LC3, BNIP3L, ATG16L, BNIP3, NF-κB, and HIF-1α, which promote the degradation of caveolin-1 (Cav-1), leading to autophagy activation." (PMID 32707662, 2020). "CAV1 expression in cancer cells reduces HIF1α transcriptional activity in hypoxia by reducing HIF1α S-nitrosylation and, as a consequence, the transcription of VEGF, which likely limits tumor growth and contributes to the tumor suppressor function of CAV1 in the absence of E-cadherin." (PMID 32825247, 2020). "Therefore, ACAT1 appears to increase the tumor-promoting function of CAV1, by favoring LDL uptake, as reported in endothelial cells, and also the formation and stabilization of lipid droplets, which aid in sustaining tumor cell proliferation under adverse conditions." (PMID 32458269, 2020). "Furthermore, in vivo inhibition of NOS with L-NAME reduced tumor growth in cells lacking CAV1 to a similar extent as observed for CAV1-expressing cells." (PMID 32825247, 2020). "Additional control studies in a HER2-negative/CAV1-positive MDA-MB-231 orthotopic mammary fat pad model demonstrated that 89Zr-labeled pertuzumab accumulation does not increase on lovastatin treatment in a HER2-negative tumor model." (PMID 31171598, 2019). "Also, Cav-1 is demonstrated to restrain the conversion of low glycosylation CD147 to high glycosylation, inhibiting MMP induction and ECM degradation and acting as tumor suppressor because high glycosylation CD147 can stimulate the induction of MMP." (PMID 31759347, 2019). "Although the clinical relevance of Cav-1 expression was not verified according to the histological classification, our study suggested that high Cav-1 expression in tumor cells is definitively related in BM of SQC type and can be a poor independent prognostic factor in NSCLC." (PMID 31297035, 2019). "Importantly, the role for CAV1 in tumor suppression is not based exclusively on in vitro experiments." (PMID 31362353, 2019). "However, long-term treatment with pioglitazone or metformin failed to enhance the tumor suppressor, cav-1, at high concentrations of glucose and insulin." (PMID 30729133, 2019). "Thus, a question remains whether the function of PTBP3 in gastric carcinoma tumour formation and metastasis is related to PTBP3-regulated alternative splicing of CAV1." (PMID 29752441, 2018). "We observed that BM Cav1 deletion in these mice did not affect PyMT primary tumor growth or weight." (PMID 29212030, 2017).